CCND1 (cyclin D1)
Diseases named in the same sentence as CCND1 in open-access papers (continued):
Sharing a sentence is not in itself a finding about the gene and the disease.
brain tumor (13 papers, 2013 to 2025). "The present study was designed to determine the association between the genetic polymorphisms/expression variations of RB1 and CCND1 genes and brain tumor risk." (PMID 32373934, 2020). "The present study was designed to explore the correlation between the genetic polymorphism of RB1 and CCND1 genes to brain tumor risk in Pakistani population." (PMID 32373934, 2020). "Second selected SNP of CCND1 polymorphism rs498136, was also showed significant association in brain tumor patients in homozygous mutant genotype in present study." (PMID 32373934, 2020). "The results showed homozygous mutant genotype of RB1 gene polymorphism, rs121913300 (P=0.003) and CCND1 gene polymorphism rs614367 (P=0.01) were associated significantly with brain tumor risk." (PMID 32373934, 2020). "In case of rs498136 polymorphism of CCND1, ∼8.23-fold increased risk of brain tumor was observed associated with homozygous mutant genotype (OR, 8.23; 95% CI, 1.02–66.31; P=0.047) in brain tumor patients compared with controls." (PMID 32373934, 2020). "Genotype frequency of CCND1 polymorphism rs614367 showed ∼4.88-fold increased risk of brain tumor with homozygous mutant genotype (OR, 4.88; 95% CI, 1.39–17.21; P=0.01) in sampled tumor patients." (PMID 32373934, 2020). "The present study encompasses the genetic analysis of RB1 exonic and CCND1 intergenic polymorphisms in brain tumor patients to find their association with brain carcinogenesis." (PMID 32373934, 2020). "As far as we know, this is so far the most comprehensive meta‐analysis about CCND1 polymorphism and brain tumor." (PMID 30972946, 2019). "Recently, some studies already tried to assess the associations between CCND1 polymorphisms and brain tumor." (PMID 30972946, 2019). "Some studies already tried to assess the associations between cyclin D1 (CCND1) polymorphisms and brain tumor." (PMID 30972946, 2019). "First, the present meta‐analysis aimed to explore associations between all CCND1 polymorphisms and brain tumor." (PMID 30972946, 2019). "However, till now, no study has been reported to screen out the hotspot polymorphisms of RB1 and CCND1 genes along with expression variations of respective genes in brain tumor and different subtypes of brain tumor." (PMID 32373934, 2020). "In conclusion, it is suggested that polymorphisms/expression variations of RB1 and CCND1 genes may be associated with increased risk of brain tumor." (PMID 32373934, 2020). "Thus, we performed the present meta‐analysis to explore the relationship between CCND1 polymorphisms and brain tumor in a larger pooled population." (PMID 30972946, 2019). "Third, associations between CCND1 rs603965 polymorphism and brain tumor may also be modified by gene‐environmental interactions." (PMID 30972946, 2019). "Present study was designed to find out whether the polymorphisms or expressional variation in the RB1 and CCND1 genes can modify the risk for brain tumor, and if the effects of these polymorphisms differ in different pathological parameters of brain tumor patients." (PMID 32373934, 2020). "Moreover, CCND1 polymorphism rs614367 showed significant association of all three genetic models, i.e. dominant (P=0.002), recessive (P=0.01) and additive (P=0.0007) with increased risk of brain tumor." (PMID 32373934, 2020). "Expression levels of RB1 and CCND1 gene was also measured in cohort II of brain tumor patients and controls using qPCR and immunohistochemistry." (PMID 32373934, 2020). "Further analysis showed significantly increased CCND1 mRNA level in grade IV (P=0.03) brain tumor patients compared with other grades." (PMID 32373934, 2020). "Expression level of RB1, CCND1 and Ki-67 was also observed in 96 brain tumor section and adjacent control section using IHC." (PMID 32373934, 2020).
brain tumor (continued). "The RB1 mRNA level was negatively correlated with grades (r = −0.252**, P<0.01), however positive correlation was observed for CCND1 mRNA level and grades (r = 0.222*, P<0.05) of brain tumor patients." (PMID 32373934, 2020). "RB1 and CCND1 mRNA levels were observed in study cohort II including 96 brain tumor tissues and adjacent uninvolved healthy section used as control." (PMID 32373934, 2020). "In case of second selected molecule, CCND1 gene, significant up-regulation was observed in brain tumor patients compared with controls using qPCR and immunohistochemistry." (PMID 32373934, 2020). "In case of second selected gene CCND1, significantly higher mRNA level was observed in brain tumors section compared with adjacent control section (P=0.0003)." (PMID 32373934, 2020). "Correlations were tested between RB1, CCND1 and Ki-67, clinical and pathological features of brain tumor patients group II." (PMID 32373934, 2020). "Genetic variations in the CCND1 gene may lead to alternations in gene expression or changes in CCND1 protein structure, which may subsequently affect biological functions of CCND1 and ultimately impact individual susceptibility to multiple malignancies including brain tumor." (PMID 30972946, 2019). "We have previously shown that FAK regulates brain tumor cellular proliferation through cyclin D1 and p27Kip134." (PMID 25677816, 2015). "Additionally, the destructive properties of subventricular NPCs against GBM cells appeared dependent on the expression of D-type cyclins, in particular cyclin D1 (cD1) and cD2, genes that act as key brain tumor oncogenes." (PMID 35011697, 2022). "Moreover, significant down-regulation of RB1 (P=0.005) and up-regulation of CCND1 (P=0.0001) gene was observed in brain tumor sections vs controls." (PMID 32373934, 2020). "Expression levels of selected genes were also assessed at protein level using immunohistochemical analysis (IHC) and signification down-regulation of RB1 (P=0.0001) and up-regulation of CCND1 (P=0.0001) was observed in brain tumor compared with control sections." (PMID 32373934, 2020). "Expression levels of RB1 and CCND1 were also analyzed in brain tumor patients." (PMID 32373934, 2020). "Previous studies failed to reach a consensus regarding associations between CCND1 polymorphisms and brain tumor partially because of their relatively small sample sizes." (PMID 30972946, 2019). "Of importance, this was accompanied by a significant reduction of CCND1 and of MGMT expressions in the core of mice brain tumors (TM) thereby corroborating, in an integrated context, data obtained in vitro." (PMID 40108111, 2025). "In study cohort II, 96 brain tumor tissues and 96 healthy tissues were analyzed for the expression variation of RB1 and CCND1 genes." (PMID 32373934, 2020). "In study cohort I, 250 brain tumor patients and 250 control individuals were examined for four selected SNPs including rs137853294, rs121913300 (RB1), rs614367 and rs498136 (CCND1)." (PMID 32373934, 2020). "A significant negative correlation was observed between CCND1 vs RB1 (r = −0.54***, P<0.0001) and RB1 vs Ki-67 (r = −0.29*, P<0.05) in brain tumor patients." (PMID 32373934, 2020).
Burkitt lymphoma (13 papers, 2002 to 2025). A rare form of malignant mature B-cell non-Hodgkin lymphoma. "Cells should also be identified with Burkitt’s lymphoma because cyclin D1 is also expressed in this disease." (PMID 25859411, 2015). "Inula viscosa extract supresses cell cycle and proliferation genes (c-MYC, CCND1) while inhibiting anti-apoptotic genes (BCL2, BCL2L1, BCL11 A), demonstrating significant anticancer effects on Burkitt’s lymphoma (BL) cells." (PMID 40214725, 2025). "SOX11 is expressed in cyclin D1-negative MCL (classic and blastoid variant) but can be seen in other blastoid neoplasms such as Burkitt lymphoma." (PMID 37530792, 2024). "Similarly, western blot results of Burkitt's lymphoma (BL) cell line BL41 and BL41 infected with wild-type EBV strain B95.8 (BL41/B95.8) also showed elevated levels of Cyclin Ds with Cyclin D1 expression more dramatically changed compared to other Cyclin Ds." (PMID 21347341, 2011). "We then examined the effect of iron depletion on the cell lines which do not have constitutively active cyclin D1, and we used SUDHL‐6 originating from diffuse large B‐cell lymphoma and DG‐75 isolated from Burkitt's lymphoma." (PMID 31517438, 2019).
colon adenocarcinoma (13 papers, 2006 to 2023). "As a positive regulator of Cdk 4and Cdk 6, cyclin D1 has been implicated in controlling the G1 phase ofthe cell cycle as shown in human colon adenocarcinomas." (PMID 21455311, 2011). "However, limited number of studies have examined the association of cyclin D1 expression and prognosis of patients with different malignant tumors, while others have evaluated it in colon adenocarcinoma with equivocal results." (PMID 16426443, 2006). "(E) Data for the LAST and CCND1 expression levels in COAD (colon adenocarcinoma) tumor and normal tissues were downloaded from the TCGA dataset." (PMID 29199958, 2017). "In colon adenocarcinoma, cytoplasmic-membranous Ccnd1 protein expression was evaluated in 50 samples, with different types of invasion (collective, pushing, budding, glandular)." (PMID 27105504, 2016). "The expression of upstream survival signals (GSK-3β, β-catenin, c-myc and cyclin D1) in human colon adenocarcinoma Caco-2 cells was evaluated after epirubicin treatment with or without galectin-3 knockdown." (PMID 24303084, 2013). "In the present study, cyclin D1 and pRb expression was assessed immunohistochemically in tumoral tissues obtained from colon adenocarcinoma patients." (PMID 16426443, 2006). "ZNF692 promotes cell proliferation, migration, and invasion in colon adenocarcinoma (COAD) by downregulating p27kip1 or upregulating cyclin D1, cyclin-dependent kinase 2 (CDK2), matrix metalloproteinase-9 (MMP-9), and PI3K/Akt signaling." (PMID 36358661, 2022). "Anti-tumor effects were also reported for hydroxytyrosol (HT), who reduced the proliferation of human colon adenocarcinoma cells through the inhibition of extracellular signal-regulated kinases (ERK) 1/2 and cyclin D1." (PMID 34202787, 2021). "Moreover, similar TCF4 silencing experiments performed in SW480 colon adenocarcinoma cells also decreased RHBG, Axin2 and Cyclin D1 mRNA levels." (PMID 26029888, 2015).
diffuse large B-cell lymphoma (13 papers, 2010 to 2026). "Similarly, it has been previously revealed that HULC knockdown induced cell growth arrest and apoptosis through inhibiting CCND1 expression in diffuse large B-cell lymphoma cells." (PMID 36438902, 2022). "Rare cases of diffuse large B-cell lymphomas could be positive for cyclin D1, but they frequently lack CCND1 gene translocation and lack immunoreactivity for SOX-11." (PMID 34442137, 2021). "Likewise, in B-cell malignancies, proto-oncogenes are often translocated to the locus of the immunoglobulin heavy chain (IGH), such as MYC in Burkitt lymphoma (IGH/MYC), CCND1 in mantle cell lymphoma, BCL-6 in diffuse large B-cell lymphoma (DLBCL) and BCL-2 in follicular lymphoma." (PMID 35563017, 2022).
gallbladder cancer (13 papers, 2010 to 2025). "Over-expression of cyclin D1 is an early event in carcinogenesis in human colorectal, esophageal and gallbladder cancers, and is a prognostic indicator associated with poor survival in esophageal, breast, and urinary cancers." (PMID 23383271, 2013). "Taken together, ARAF silencing suppresses the malignant phenotypes of gallbladder cancer cells, and the mechanism may be associated with regulating Erk/cyclin D1 axis." (PMID 32923479, 2020). "Kaempferol has been shown to hinder cell growth and induce apoptosis in human gallbladder cancer cells via Cyclin D1/CDK4 signaling pathway." (PMID 39161904, 2024). "In addition, As2O3 down-regulates cyclin D1 transcription via a reduction of Sp1 transcription factor in gallbladder carcinoma cells." (PMID 26359868, 2015). "The transition from the G0 to G1 phase of the cell cycle is regulated in part by a mitosis-promoting factor, which consists of cyclin D1 and CDK4 in gallbladder cancer cells." (PMID 29899865, 2018).
gastric tumors (13 papers, 2010 to 2024). "Another study implicated the role of STAT3 signaling in angiogenesis of gastric tumors by regulation of its target genes cyclin D1, Bcl-xL and VEGF." (PMID 29383166, 2017). "Immunohistochemistry for cyclin D1 showed nuclear immunoreactivity in proliferating gastric tumor cells." (PMID 20704706, 2010). "Another investigation has demonstrated that silence of the expression of Stat3 suppresses the proliferation of gastric tumors, and induces cell apoptosis and cell cycle shift induction both in vivo and in vitro significantly by regulating downstream protein Cyclin-D1, Survivin, and Bcl-2." (PMID 38238515, 2024). "Elevated expression of Cyclin D1 in human gastric tumors correlates with a particularly poor prognosis, therefore understanding factors that increase Cyclin D1 expression may lead to therapeutic avenues for this and other forms of cancer." (PMID 20625512, 2010). "In the gastric tumors, many of these genes are regulated by ETS2, BMP4, and TGFB1 and by the kinases MAPK1(ERK) and CCNK and the transcription regulators E2F, CBX5, and CCND1." (PMID 31584998, 2019). "However, in gastric tumor, MLXIPL inhibits proliferation and promotes apoptosis via targeting the cyclin D1-Rb-E2F1 pathway." (PMID 38698844, 2024). "Similarly, a reduction in MG53 protein abundance and negative correlation between MG53 and cyclin D1 levels were observed in gastric tumors." (PMID 37414783, 2023).
kidney cancer (13 papers, 2013 to 2025). Primary or metastatic malignant neoplasm involving the kidney. "The cell-intrinsic antiproliferative effects of HIF2 inhibitors in kidney cancer are caused by loss of cyclin D1 activity, and upregulation of cyclin D2 or D3 are potential resistance mechanisms." (PMID 40178040, 2025). "Moreover, HIF-2α is sufficient to maintain tumor growth in VHL-deficient kidney cancer cells via Cyclin D1 activation." (PMID 36831657, 2023). "In fact, FOXM1 is overexpressed in various human malignancies, including prostate, breast, lung, ovary, colon, pancreas, stomach, bladder, liver and kidney cancer, and its oncogenic activity is downstream of Ras and cyclin D1, which are often implicated in epithelial tumors." (PMID 27385468, 2016). "In kidney cancer (ccRCC), miR-184 suppresses proliferation, migration, and invasion through downregulation of CCND1 and targeting oncogenic pathways, although sponging by LINC01094 and SLC2A3 promotes tumour progression." (PMID 41379397, 2025). "We discovered that cyclin D1 is the key target of HIF2 driving the cell-autonomous proliferation of VHL-mutant kidney cancers and that cyclin D1 has targets beyond pRB in this setting." (PMID 40178040, 2025). "In liver and kidney cancer, FAM83H expression was associated with the expression of cyclin D1, cyclin E1, and downstream signaling of the Wnt/β-catenin pathway." (PMID 31215499, 2019). "Additionally, the HIF-2α antagonist, PT2399, reduces CCND1 levels in pre-clinical kidney cancer models." (PMID 36831657, 2023). "FOXM1 is overexpressed in various human malignancies, including prostate, breast, lung, colon, stomach, liver, and kidney cancer, via the activation of Ras and cyclin D1 and FOXM1-depletion is sufficient to decrease carcinogenesis by stimulating apoptosis 45-47." (PMID 37908734, 2023). "For example, an L-M-FFL motif comprised of KB-1732A1.1, MYC, miR-93, and CCND1 was only dysregulated in lung squamous cell carcinomas, and an L-M-FFL motif including LINC00662, MYC, miR-34a and VEGF was only dysregulated in kidney cancer." (PMID 27322142, 2016). "Our in silico docking study shown CCND1 protein as an attractive anticancer target and natural flavanoids rutin and curcumin as potential anticancer drug of RCC and they may be promising in the prevention of kidney cancer too." (PMID 27766950, 2016).
liposarcoma (13 papers, 2011 to 2025). A usually painless malignant tumor that arises from adipose tissue. "A lncRNA transcribed from the 5′ promoter region of CCND1 recruits TLS (for translocated in liposarcoma) to the CCND1 promoter by inhibiting histone acetyltransferase activities and caused CCND1 transcription inhibition." (PMID 28830551, 2017). "A study has reported that miR-155 can accelerate liposarcoma development by inhibiting CK1α expression in liposarcoma cells to increase the expression and activity of cyclin D1 and β-catenin." (PMID 39736850, 2025). "The lipomas and well-differentiated liposarcomas that were immunohistochemically analyzed for CCND1 showed scattered positivity in a majority of cases 32/49 (65%), whereas 16/49 (33%) stained negative for CCND1 and 1/49 stained positive." (PMID 21559269, 2011). "Wnt/β-catenin signaling has been associated with miR-155 in liposarcoma; CK1α (casein kinase 1α), a key regulator of Wnt/β-catenin pathway, is targeted by miR-155, leading to β-catenin signaling and CCND1 activation, cell proliferation and liposarcoma progression." (PMID 27081085, 2016). "In liposarcoma casein kinase 1-α (CK1-α) is targeted by miR-155, enhancing beta-catenin and cyclin D1." (PMID 28259135, 2017). "ncRNACCND1s recruits a key transcriptional sensor of DNA damage, the translocated in liposarcoma (TLS) RNA-binding protein, to the promoter region of cyclin D1 (CCND1)." (PMID 23087702, 2012). "Furthermore, LINC01488 is reported to bind translocated in liposarcoma (TLS) and induce transcriptional repression through HAT inhibitory activity in addition to negatively regulating Cyclin D1 transcription to inhibit cell growth." (PMID 32575745, 2020).
pancreatic adenocarcinoma (13 papers, 2010 to 2025). "According to previous studies that support our findings, CCND1 overexpression in pancreatic adenocarcinoma correlates with aggressive features and poorer survival, indicating its potential as an adverse prognostic factor." (PMID 39188436, 2024). "Silibinin caused G1 arrest by decreasing the expression of Cyclin D1, Cyclin E2 and CDK4 and inducing increased expression of p21 and p15 in the human pancreatic adenocarcinoma cell line SW1990." (PMID 35401195, 2022). "Conversely, the expression levels of CCND1, DUSP2, ETS2, JUN, and RALGDS were decreased in lung and pancreatic adenocarcinomas with KRAS mutations." (PMID 33982211, 2021). "After the OS analysis of these 10 target genes, we found that 4 were OS-associated genes in pancreatic adenocarcinoma: ARHPAG32, HOXA10, CCND1 and CEP55." (PMID 29769534, 2018). "Expression of this cell surface glycoprotein also led to activation of the ERK MAPK pathway promoting cell cycle progression by increasing the levels of cyclin D1 and cyclin E in the murine pancreatic adenocarcinoma cell line Panc02." (PMID 20858281, 2010). "Our findings are in line with a previous study in pancreatic adenocarcinoma, which found that CCND3 suppression did not result in compensatory upregulations in CCND1 expression." (PMID 35406445, 2022).